FGF1 (fibroblast growth factor 1)
Description:
Plays an important role in the regulation of cell survival, cell division, angiogenesis, cell differentiation and cell migration. Functions as a potent mitogen in vitro. Acts as a ligand for FGFR1 and integrins. Binds to FGFR1 in the presence of heparin leading to FGFR1 dimerization and activation via sequential autophosphorylation on tyrosine residues which act as docking sites for interacting proteins, leading to the activation of several signaling cascades. Binds to integrin ITGAV:ITGB3. Its binding to integrin, subsequent ternary complex formation with integrin and FGFR1, and the recruitment of PTPN11 to the complex are essential for FGF1 signaling. Induces the phosphorylation and activation of FGFR1, FRS2, MAPK3/ERK1, MAPK1/ERK2 and AKT1. Can induce angiogenesis.
Synonyms: FGF-1; aFGF; ECGF; HBGF-1; FGFA; ECGFA; ECGFB; HBGF1; ECGF-beta; FGF-alpha; GLIO703
Tractability: Small molecule: a drug acting on it is in phase 2 or 3 trials; a structure with a bound ligand is known; a high-quality ligand is known; it has a binding pocket of medium quality; it belongs to a druggable protein family. Antibody: a drug acting on it is in phase 2 or 3 trials; its Gene Ontology location is reachable by antibodies, with high confidence; UniProt places it where antibodies can reach, with medium confidence. PROTAC: a small molecule that binds it is known. Other modalities: a drug acting on it is in phase 2 or 3 trials.
Target class: Secreted protein
Chemical probes: PD008555, PD052855
Gene: Protein-coding gene on chromosome 5 (142,592,166 to 142,698,070, reverse strand). Ensembl gene ENSG00000113578.
Subcellular location: Secreted; Cytoplasm; Cytoplasm, cell cortex; Cytoplasm, cytosol; Nucleus
Subcellular location (Human Protein Atlas): Nucleoplasm; Predicted to be secreted
Pathways (Reactome):
Signal Transduction: Downstream signaling of activated FGFR1; FGFR1b ligand binding and activation; FGFR1c ligand binding and activation; FGFR2b ligand binding and activation; FGFR2c ligand binding and activation; FGFR3b ligand binding and activation; FGFR3c ligand binding and activation; FGFR4 ligand binding and activation; FRS-mediated FGFR1 signaling; FRS-mediated FGFR2 signaling; FRS-mediated FGFR3 signaling; FRS-mediated FGFR4 signaling; Negative regulation of FGFR1 signaling; Negative regulation of FGFR2 signaling; Negative regulation of FGFR3 signaling; Negative regulation of FGFR4 signaling; PI-3K cascade:FGFR1; PI-3K cascade:FGFR2; PI-3K cascade:FGFR3; PI-3K cascade:FGFR4; PI3K Cascade; PI5P, PP2A and IER3 Regulate PI3K/AKT Signaling; PIP3 activates AKT signaling; Phospholipase C-mediated cascade: FGFR1; Phospholipase C-mediated cascade; FGFR2; Phospholipase C-mediated cascade; FGFR3; Phospholipase C-mediated cascade; FGFR4; RAF/MAP kinase cascade; SHC-mediated cascade:FGFR1; SHC-mediated cascade:FGFR2; SHC-mediated cascade:FGFR3; SHC-mediated cascade:FGFR4
Disease: Activated point mutants of FGFR2; Constitutive Signaling by Aberrant PI3K in Cancer; Signaling by FGFR1 in disease; Signaling by FGFR2 IIIa TM; Signaling by FGFR2 in disease; Signaling by FGFR3 in disease; Signaling by activated point mutants of FGFR1; Signaling by activated point mutants of FGFR3
Gene Ontology:
Molecular function: fibroblast growth factor receptor binding; growth factor activity; heparin binding; integrin binding; protein binding; S100 protein binding
Biological process: activation of protein kinase B activity; branch elongation involved in ureteric bud branching; cellular response to heat; fibroblast growth factor receptor signaling pathway; mesonephric epithelium development; positive regulation of angiogenesis; positive regulation of cell division; positive regulation of cell migration; positive regulation of cell population proliferation; positive regulation of cholesterol biosynthetic process; positive regulation of endothelial cell migration; positive regulation of ERK1 and ERK2 cascade; positive regulation of intracellular signal transduction; positive regulation of MAP kinase activity; positive regulation of sprouting angiogenesis; positive regulation of transcription by RNA polymerase II; regulation of endothelial cell chemotaxis to fibroblast growth factor; regulation of endothelial tube morphogenesis; wound healing; anatomical structure morphogenesis; neurogenesis; positive regulation of MAPK cascade; regulation of cell migration; signal transduction; branching involved in ureteric bud morphogenesis; and 1 more
Cellular component: cytosol; extracellular region; nucleoplasm; cytoplasm; nucleus; cell cortex; extracellular matrix
Genetic constraint (gnomAD): Loss-of-function variants: 5 observed, 10.09 expected, observed/expected ratio (o/e) 0.5, 90% interval 0.26 to 1.04. The upper end of that interval is the gene's LOEUF score, 1.04, which puts it in group 4 of 6, group 1 being the genes least tolerant of losing a copy. Missense variants: 149 observed, 193.76 expected, observed/expected ratio (o/e) 0.77, 90% interval 0.67 to 0.88. Synonymous variants: 88 observed, 78.88 expected, observed/expected ratio (o/e) 1.12, 90% interval 0.94 to 1.33.
Homologues: Orthologues: chimpanzee FGF1 (100% identical), macaque FGF1 (99% identical), dog FGF1 (99% identical), pig FGF1 (98% identical), rabbit FGF1 (97% identical), mouse Fgf1 (95% identical), guinea pig FGF1 (95% identical), rat Fgf1 (95% identical), tropical clawed frog fgf1 (75% identical). Paralogues in human: FGF2 (54% identical), FGF16 (39% identical), FGF20 (39% identical), FGF9 (38% identical), FGF13 (34% identical), FGF14 (33% identical), FGF7 (33% identical), FGF22 (32% identical), FGF3 (31% identical), FGF10 (30% identical), FGF12 (30% identical), FGF5 (30% identical), and 9 more.
Diseases named in the same sentence as FGF1 in open-access papers:
FGF1 is named in the same sentence as 238 diseases in open-access papers, as found by Europe PMC text mining. Sharing a sentence is not in itself a finding about the gene and the disease. The quoted sentences say what the papers report.
breast cancer (56 papers, 1995 to 2026). A primary or metastatic malignant neoplasm involving the breast. "The findings emphasize the significant involvement of FGF1 and FGFRs in drug resistance in breast cancer; however, the mechanisms underlying this phenomenon appear to be intricate and require further understanding." (PMID 37509496, 2023). "FGF1 is associated with tumour development, as it is upregulated in various cancers, including breast cancer, gliomas and ovarian cancer." (PMID 32660514, 2020). "Besides iCCA, FGF1 sustains the survival of dormant cancer cells in breast cancer, modulates senescence-associated malignancy in prostate cancer, and reactivates RAF-MEK signaling in pancreatic ductal adenocarcinoma to bypass targeted inhibition." (PMID 41430037, 2025). "Together, these data show that FGF1 signaling involves ER activation in endocrine-resistant obesity-associated breast cancers, and that one consequence may be metabolic reprogramming toward an aggressive glycolytic tumor phenotype." (PMID 37608351, 2023). "On the other hand, FGF1 treatment increases basal OCR in breast cancer cells through activation of the estrogen receptor." (PMID 39433211, 2025). "FGF1 treatment increases the basal ECAR in breast cancer cell lines, while FGF2 treatment increases lactate production in murine adipocytes, rat Sertoli cells, and human squamous cell carcinoma cells." (PMID 39433211, 2025). "Phospho- and total proteomic, genomic, and functional analyses of endocrine-sensitive and resistant breast cancer cells show that FGF1 promoted a cellular phenotype characterized by glycolytic metabolism." (PMID 37608351, 2023). "We explored the effects of FGF1 on ER-positive endocrine-sensitive and resistant breast cancer and compared that to the effects of the canonical ER ligand, estradiol." (PMID 37608351, 2023). "Here, we show that FGF1 can stimulate ER phosphorylation and activation in some breast cancer cells and we suggest that one important effect is metabolic reprogramming of aggressive cancer cells toward a glycolytic phenotype." (PMID 37608351, 2023). "There is compelling evidence demonstrating the role of FGF1 and FGF2 as potent angiogenic factors in mediating increased breast cancer risk and progression." (PMID 37800138, 2023). "Note that we did not evaluate the impact of GPER1 overexpression on the localization of PRKCSH, but it has been reported for breast cancer cells that PRKCSH can translocate to the nucleus in a complex with the fibroblast growth factor 1 and its receptor FGFR." (PMID 37947649, 2023). "In ER+ breast cancer cells, CAAs secrete fibroblast growth factor 1 (FGF1), which phosphorylates the fibroblast growth factor receptor (FGFR)." (PMID 38001753, 2023). "In particular, we have demonstrated for the first time the protective role of FGF1 in MCF-7 breast cancer cells against cytotoxicity induced by taltobulin, which is mediated by the activation of FGFRs and subsequent ERKs and AKT activation." (PMID 37509496, 2023). "In multiple ER+ breast cancer cell lines, FGF1 and FGF2 can induce membrane ruffling, which often accompanies metastatic invasion." (PMID 37800138, 2023). "Undoubtedly, however, further research is required to fully elucidate the role of FGF1 in breast cancer biology and its potential as a therapeutic target." (PMID 37509496, 2023). "A similar inverse interaction between FGF1 and periostin has been observed in breast cancer where FGF1 repressed periostin expression through a PKC-dependent pathway." (PMID 35883655, 2022). "MEK inhibitors were ineffective in overcoming endocrine resistance in breast cancer cell lines stimulated by growth factors such as fibroblast growth factor 1 (FGF-1) and heregulin β1 (HRGβ1)." (PMID 36358725, 2022). "Targeted therapies have been developed for suppressing the post-partum pro-tumorigenic extracellular matrix via inhibition of PTGS2, and the potential benefit of targeting the FGF1 pathway in breast cancer has been considered." (PMID 36035177, 2022).
breast cancer (continued). "It would be interesting to block either FGF or both using available single-chain variable fragment (scFv) antibodies and their dimerization form, which have been shown to inhibit FGF1-dependent breast cancer growth in vitro." (PMID 35193394, 2022). "Zhang and co-workers showed that overexpression of FGF1 promotes tumor growth in breast cancer treated with tamoxifen." (PMID 34830951, 2021). "Studies in ovarian cancer, breast cancer and lung cancer suggest that FGF1 expression levels in tumor tissues are closely related to prognosis." (PMID 34552869, 2021). "Fibroblast growth factor 1 (FGF1) is a pro-angiogenic factor that promotes MCF-7 breast cancer cell intravasation via increasing vessel density." (PMID 31835465, 2019). "Results of our study showed that stimulation of PR(+) breast cancer cell lines with various FGFs decreased level of PR with the highest impact being observed for FGF1, FGF4, FGF7." (PMID 27852068, 2016). "To confirm the importance of integrin αvβ3 to mediate FGF1 signaling in cancer cells, we establish stably knockdown of integrin β3 into SK-BR-3-breast cancer cells, in which αvβ3 is moderately expressed." (PMID 26334633, 2015). "In breast cancer cells, FGF1 plays similar role in the mitochondrial localization of MUC1 using similar molecular mechanism." (PMID 25261375, 2014). "MCF-7/GFP-scFv1C9 cells have a significantly lower tumourigenicity than MCF-7/GFP cells, suggesting that FGF-1 is important for the development of breast cancer and that blocking FGF-1 with a specific antibody is an effective strategy to inhibit breast cancer." (PMID 25124967, 2014). "FGF-1 stimulates the development of several types of cancers, including bladder cancer, hepatocellular carcinoma, pancreatic cancer and breast cancer 11–13, which suggests that FGF-1 signalling is a potential target for cancer therapy." (PMID 25124967, 2014). "FGF-1 has been reported to promote the invasion and metastasis of breast cancer by inducing MMP-9 expression." (PMID 25124967, 2014). "First, we assessed the FGF-1 mRNA levels in various breast cancer cells (MDA-MB-231, BT549, MCF-7, and BT474)." (PMID 25124967, 2014). "In a previous study, we demonstrated that the fibroblast growth factor 1 (FGF-1)-specific recombinant antibody scFv1C9 arrests the cell cycle at the G0/G1 transition by blocking the intracrine FGF-1 pathway in breast cancer cells." (PMID 25124967, 2014). "Here, we further show that the overexpression of scFv1C9 in MCF-7 and MDA-MB-231 breast cancer cells by lentiviral infection resulted in decreased tumourigenicity, tumour growth and lung metastasis through FGF-1 neutralization." (PMID 25124967, 2014). "In breast cancer cell lines, FGF1 has been found to facilitate the targeting of MUC1-C to the nucleus." (PMID 25261375, 2014). "In our previous study, we reported that scFv1C9 effectively inhibits FGF-1 by blocking the intracrine FGF-1 pathway, thereby decreasing the proliferation of breast carcinoma cells." (PMID 25124967, 2014). "We also showed that MEK1/2 and STAT3 stimulation in response to FGF1 stimulation is increased in HEK293 cells expressing the FGFR2-IIIb breast cancer mutants." (PMID 23527311, 2013). "Previously, we described FGF-1- or FGF-4-transfected MCF-7 breast carcinoma cells which are tumorigenic and metastatic in untreated or tamoxifen-treated ovariectomised nude mice." (PMID 8624263, 1996). "Thus, it can be concluded that the contribution of FGF1 to breast cancer angiogenesis is dominant at a young age compared to FGF2 which plays a greater role at an older age." (PMID 39302921, 2024). "In all three breast cancer cell lines examined, FGF1 treatment upregulated genes involved in cell proliferation (e.g., E2F targets, G2M checkpoint) and metabolism (e.g., cholesterol homeostasis, glycolysis), but there was not a significant enrichment of genes linked to invasion or metastasis." (PMID 37608351, 2023).
breast cancer (continued). "Understanding the interplay between FGF1 signaling pathways may pave the way for the development of more effective targeted therapies for breast cancer patients." (PMID 37509496, 2023). "FGF1 could facilitate neoplastic progression, thus playing an important role in human salivary glands and breast cancer." (PMID 38155938, 2023). "Our study demonstrates a protective role for FGF1 in MCF-7 breast cancer cells against taltobulin-induced cytotoxicity, mediated by activation of its receptors and compares its activity to EGF, another growth factor involved in breast cancer development and progression." (PMID 37509496, 2023). "Among the commonly regulated FGF1 genes was Ets variant transcription factor 4 (ETV4), which has been shown to influence ER DNA binding activity in endometrial cancer cells, and glycolytic gene expression in breast cancer cells." (PMID 37608351, 2023). "Notably, three of these genes, including IGF1, PTGS2, and FGF1, were significantly related to breast cancer patient outcomes, thus further verifying their potential roles as prognostic biomarkers." (PMID 36035177, 2022). "However, FGF-1 is overexpressed in many types of cancer tissue, such as bladder cancer, hepatocellular carcinoma, pancreatic cancer and breast cancer 3,11,25." (PMID 25124967, 2014). "In breast cancer, there is a decrease in the amount of FGF1 and FGF2 present in breast tissue." (PMID 11953856, 2002). "However, in the case of FGF1, there is evidence for some remaining in a more functionally available form in breast cancers." (PMID 11953856, 2002). "The action of FGF1 on adipocytes is also relevant within breast cancer, where FGF1 stimulates cancer cell proliferation and plays a role in the reprogramming of metabolism through activation of the estrogen receptor (ER) in the ER‐positive breast cancer subtype." (PMID 41131959, 2026). "Moreover, the important role of CUX1/FGF1/HGF signalling in promoting cell proliferation, migration and tube formation in vascular endothelial cells was strongly associated with the DPPA‐induced inhibition of tumour growth and angiogenesis in breast cancer." (PMID 30010249, 2018). "Thus, our data indicate a central role for scFv1C9 in blocking the intracrine pathway of FGF-1, therefore, scFv1C9 could be developed in an effective therapeutic for breast cancer." (PMID 25124967, 2014). "Furthermore, both breast cancer mutations implicated an increased tyrosine phosphorylation of the critical FGFR2 substrate FRS2 and an increased MEK1/2 and STAT3 activation in response to FGF1 stimulation leading to an accelerated cell signaling." (PMID 23527311, 2013). "Additionally, FGF1-gold nanoparticle conjugates targeting FGFR could efficiently decrease breast cancer cell viability, suggesting the possibility for targeted therapy." (PMID 23951052, 2013). "For instance, fibroblast growth factor-1 (FGF-1) enters cells and localizes to the nucleus to reduce the expression of p21 in breast cancer tissues." (PMID 40948935, 2025). "In a humanized breast cancer mouse model, LSD1 inhibition resulted in reduced FLI1 target gene signatures related to angiogenesis (VEGFA, FGF-1, MMP-1, MMP-9), migration, and invasion (PLAU)." (PMID 41300765, 2025). "The mRNA expression levels for eight pro-angiogenic genes [VEGFA, HGF, FGF1, FGF2, ANGPT1, ANGPT2, PDGFA, and PDGFB] were obtained from the METABRIC (Molecular Taxonomy of Breast Cancer International Consortium) dataset available at cBioPortal public domain." (PMID 39302921, 2024). "Here, we aimed to investigate the effect of FGF1 on the MCF-7 cell line, which is widely used in research as a model of the A-luminal type of breast cancer." (PMID 37509496, 2023). "In the context of breast cancer, the expression of FGF5 and FGF6 was detected at very low level in comparison with FGF1 and FGF2." (PMID 35193394, 2022).